ENSG00000261889 (novel transcript)
Gene: Long non-coding RNA gene on chromosome 16 (3,156,736 to 3,157,483, reverse strand). Ensembl gene ENSG00000261889.
Gene Ontology:
Molecular function: triplet codon-amino acid adaptor activity
Biological process: translation